FLT4 (fms related receptor tyrosine kinase 4)
Description:
Tyrosine-protein kinase that acts as a cell-surface receptor for VEGFC and VEGFD, and plays an essential role in adult lymphangiogenesis and in the development of the vascular network and the cardiovascular system during embryonic development. Promotes proliferation, survival and migration of endothelial cells, and regulates angiogenic sprouting. Signaling by activated FLT4 leads to enhanced production of VEGFC, and to a lesser degree VEGFA, thereby creating a positive feedback loop that enhances FLT4 signaling. Modulates KDR signaling by forming heterodimers. The secreted isoform 3 may function as a decoy receptor for VEGFC and/or VEGFD and play an important role as a negative regulator of VEGFC-mediated lymphangiogenesis and angiogenesis. Binding of vascular growth factors to isoform 1 or isoform 2 leads to the activation of several signaling cascades; isoform 2 seems to be less efficient in signal transduction, because it has a truncated C-terminus and therefore lacks several phosphorylation sites. Mediates activation of the MAPK1/ERK2, MAPK3/ERK1 signaling pathway, of MAPK8 and the JUN signaling pathway, and of the AKT1 signaling pathway. Phosphorylates SHC1. Mediates phosphorylation of PIK3R1, the regulatory subunit of phosphatidylinositol 3-kinase. Promotes phosphorylation of MAPK8 at 'Thr-183' and 'Tyr-185', and of AKT1 at 'Ser-473'.
Synonyms: VEGFR-3; FLT-4; VEGFR3; PCL; CHTD7; FLT41; LMPH1A; LMPHM1
Tractability: Small molecule: an approved drug acts on it; a high-quality ligand is known; it belongs to a druggable protein family. Antibody: a drug acting on it is in phase 1 trials; UniProt places it where antibodies can reach, with high confidence; its Gene Ontology location is reachable by antibodies, with high confidence; UniProt predicts a signal peptide or a membrane-spanning region. PROTAC: ubiquitination databases record sites on it; a small molecule that binds it is known.
Target class: Tyrosine protein kinase VEGFR family; Enzyme; TK protein kinase group; Protein Kinase; Kinase
Chemical probes: TIVOZANIB
Safety:
Unwanted effects reported when the protein is acted on. In parentheses: how it was acted on, where the effect was seen, and who reports it.
heart disease (cardiovascular system; source: Force et al. (2011))
Gene: Protein-coding gene on chromosome 5 (180,601,506 to 180,649,629, reverse strand). Ensembl gene ENSG00000037280.
Subcellular location: Cell membrane; Cytoplasm; Nucleus; Cell membrane (Isoform 1); Cell membrane (Isoform 2); Secreted (Isoform 3)
Subcellular location (Human Protein Atlas): Cytosol; Centrosome; Plasma membrane; Predicted to be secreted
Pathways (Reactome):
Signal Transduction: NOTCH4 Intracellular Domain Regulates Transcription; VEGF binds to VEGFR leading to receptor dimerization
Cellular responses to stimuli: High laminar flow shear stress activates signaling by PIEZO1 and PECAM1:CDH5:KDR in endothelial cells
Gene Ontology:
Molecular function: growth factor binding; protein binding; protein homodimerization activity; protein phosphatase binding; protein tyrosine kinase activity; transmembrane receptor protein tyrosine kinase activity; vascular endothelial growth factor receptor activity; ATP binding; protein kinase activity
Biological process: cellular response to vascular endothelial growth factor stimulus; lymphangiogenesis; negative regulation of apoptotic process; peptidyl-tyrosine phosphorylation; positive regulation of cell population proliferation; positive regulation of endothelial cell migration; positive regulation of endothelial cell proliferation; positive regulation of ERK1 and ERK2 cascade; positive regulation of JNK cascade; positive regulation of MAPK cascade; positive regulation of protein phosphorylation; positive regulation of vascular endothelial growth factor production; protein autophosphorylation; vascular endothelial growth factor receptor signaling pathway; vascular endothelial growth factor signaling pathway; blood vessel morphogenesis; cell migration; cell surface receptor protein tyrosine kinase signaling pathway; lymph vessel development; positive regulation of cell migration; regulation of blood vessel remodeling; sprouting angiogenesis; vasculature development
Cellular component: cytoplasm; cytosol; nucleus; plasma membrane; receptor complex; extracellular region
Genetic constraint (gnomAD): Loss-of-function variants: 30 observed, 153.61 expected, observed/expected ratio (o/e) 0.2, 90% interval 0.14 to 0.26. The upper end of that interval is the gene's LOEUF score, 0.26, which puts it in group 1 of 6, group 1 being the genes least tolerant of losing a copy. Missense variants: 1,510 observed, 1,868.3 expected, observed/expected ratio (o/e) 0.81, 90% interval 0.77 to 0.84. Synonymous variants: 884 observed, 796.12 expected, observed/expected ratio (o/e) 1.11, 90% interval 1.05 to 1.17.
Gene-disease validity (ClinGen):
ClinGen rates the evidence that FLT4 causes each of these diseases.
congenital heart defects, multiple types, 7 (autosomal dominant): Definitive.
lymphatic malformation 1 (autosomal dominant): Definitive. Any hereditary lymphedema in which the cause of the disease is a mutation in the FLT4 gene.
Cancer hallmarks: invasion and metastasis (promotes); proliferative signalling (promotes); escaping programmed cell death (promotes)
Homologues: Orthologues: chimpanzee FLT4 (99% identical), macaque FLT4 (97% identical), dog FLT4 (88% identical), pig FLT4 (88% identical), mouse Flt4 (87% identical), rat Flt4 (87% identical), rabbit FLT4 (87% identical), guinea pig FLT4 (84% identical), tropical clawed frog flt4 (63% identical), zebrafish flt4 (54% identical). Paralogues in human: KDR (42% identical), FLT1 (39% identical), PDGFRB (23% identical), PDGFRA (23% identical), KIT (21% identical), CSF1R (20% identical), FLT3 (18% identical), FGFR1 (18% identical), FGFR2 (18% identical), FGFR3 (18% identical), FGFR4 (17% identical), ALK (15% identical), and 41 more.
Diseases named in the same sentence as FLT4 in open-access papers:
FLT4 is named in the same sentence as 308 diseases in open-access papers, as found by Europe PMC text mining. Sharing a sentence is not in itself a finding about the gene and the disease. The quoted sentences say what the papers report.
lymphedema (89 papers, 2007 to 2026). Excess fluid collection in tissues, causing swelling. "The current understanding on the phenotype, variant type, and disease prognosis of fetal-onset lymphedema caused by FLT4 mutations remains limited." (PMID 41328432, 2025). "The majority of incidences of congenital lymphedema are triggered by mutations in the FMS-like tyrosine kinase 4 (FLT4) gene." (PMID 37175479, 2023). "VEGFR3 was first implicated in Milroy disease when a region of chromosome five was linked to inherited lymphoedema cases and the FLT4 locus was chosen as the best candidate gene in this region for further investigation." (PMID 33067626, 2021). "VEGFC, which is a gene encoding the ligand for the vascular endothelial growth factor receptor 3 (VEGFR3/FLT4) and important for lymph vessel development during lymphangiogenesis, has been associated with a specific subtype of primary lymphedema." (PMID 30071673, 2018). "In this study, we utilized PC-3-derived cell lines that overexpress either the wild-type or the mutant variants of FLT4 to demonstrate that the c.3175G>C FLT4 variant exhibited reduced activity, supporting its association with the development of primary lymphedema." (PMID 41614898, 2026). "Although it has been found that certain FLT4 variants are associated with fetal lymphedema, the imaging phenotype variability, family inheritance patterns, and postnatal disease progression caused by variants in different sites remain unclear." (PMID 41328432, 2025). "Furthermore, in APOE4-expressing cells, we observed reduced expression of gene markers linked to peripheral lymphedema (e.g., VEGFR3 (FLT4)) or lymphatic valve formation (e.g., FN1, GJA1, and ITGA9)." (PMID 32355332, 2021). "Many studies have confirmed that mutations in the FLT4 gene encoding VEGFR3 cause Milroy’s disease, an inherited primary lymphedema." (PMID 40766782, 2025). "Canonical clinical entities include Milroy disease, caused by mutations in FLT4/VEGFR3, and lymphedema–distichiasis syndrome, associated with FOXC2 mutations." (PMID 41282012, 2025). "Previous evidence described the genetic screening of hereditary syndromes accompanied by the genetic mutations in genes such as FOXC2, FLT-4, and SOX18 for lymphedema-distichiasis, Milroy disease, and hypotrichosis-lymphedema-telangiectasia, respectively." (PMID 37267206, 2023). "These variants were identified through extensive genetic analysis of affected individuals, highlighting the role of the FLT4 gene in the development of the lymphatic system and the pathogenesis of hereditary lymphedema." (PMID 40041256, 2023). "Congenital mutations in FLT4, which encodes VEGFR3, have been linked to Milroy disease which is characterized by the onset of lymphedema in the lower limbs." (PMID 32824219, 2020). "Disease phenotypically consistent with Milroy’s but without a positive family history of FLT4 mutation should be termed “Milroy-like lymphedema”." (PMID 37241126, 2023). "There was a tendency of more but not significantly increases in the expression of VEGF‐C, LYVE‐1, podoplanin, PROX‐1 and FLT4 in the lymphedema group in comparison to the normal group, suggesting that lymphangiogenesis occurs when lymphatic injury, tissue injury or lymphedema presents." (PMID 36176614, 2022). "The absence of lymphedema history in our adult cohort, including those with FLT4 variants, would suggest at most a mild or fully remitted lymphedema phenotype." (PMID 30232381, 2019). "This study employs model cell lines that overexpress either wild-type FLT4 or the mutant FLT4 variant c.3175G>C to evaluate its functional activity, thereby elucidating the pathogenic role of c.3175G>C in VEGFR3 dysfunction and the development of primary lymphedema." (PMID 41614898, 2026). "Therefore, the amount of the mutant receptor on the endothelial cell surface would be considerably higher and may contribute to the development of lymphoedema by reducing the relative amount of ligand binding to the active wild-type FLT4/VEGFR3." (PMID 34103024, 2021).
lymphedema (continued). "TIMP3 mutations cause Sorby's fundus dystrophy, a disease, where choroidal vessel integrity is affected; SOX18 inactivation leads to lymphedema-distichiasis syndrome, with clinical signs of edema and abnormal morphology of capillaries and arterioles and FLT4 mutations cause Nonne-Milroy lymphedema." (PMID 19924294, 2009). "Secondary angiosarcomas (e.g., radiation and lymphedema induced) are characterized by Myc proto-oncogene (MYC) amplification and a subset also have FMS related receptor tyrosine kinase 4 (FLT4) amplification." (PMID 33931674, 2021). "Using a novel FLT4-DTR mouse model of lymphedema, we found that LNT after lymphatic injury leads to reversal of several key pathologic features of lymphedema, including swelling, skin changes, and local immunosuppression." (PMID 27942023, 2016). "Our results are particularly important because these prior studies were performed using models of lymphadenectomy rather than true lymphedema and may not reflect the clinical pathology as well as our FLT4-DTR model of lymphatic ablation." (PMID 27942023, 2016).
breast cancer (76 papers, 2003 to 2026). A primary or metastatic malignant neoplasm involving the breast. "So far, most of the studies have shown that FLT4 amplification primarily occurs in sAS, particularly those associated with radiation therapy for breast cancer or chronic lymphedema, and always in association with MYC amplification." (PMID 40666093, 2025). "Unexpectedly, FLT4 mRNA expression was reduced in a significant number of tumors compared to normal tissues across multiple organs, including the colon and breast carcinoma." (PMID 41459512, 2025). "In breast cancer, expression of VEGF-C and Flt-4 is associated with angiogenesis and lymphangiogenesis." (PMID 15841074, 2005). "In our study, FLT4 mutations were prevalent among breast angiosarcomas (n = 11, 15.1%) and did co-occur with MYC amplifications (p < 0.001), consistent with the theory that many breast angiosarcomas develop secondary to radiation for primary breast cancer." (PMID 41301029, 2025). "Nevertheless, targeting VEGFR3/FLT4/CD310 holds promise for inhibiting breast cancer metastasis." (PMID 41459512, 2025). "Also, a clinicopathological significance of VEGF-C and Flt-4 in breast cancer has been described, since their expression correlated with lymph node metastasis and decreased survival of patients." (PMID 15841074, 2005). "These included several well-known cancer genes or their family members with previously less recognized role in breast cancer—FGFR3, FGFR4, NOTCH3, KMT2B, EP300, FLT4 and FAT1." (PMID 40858906, 2025). "In the breast cancer core network, we found Fibronectin 1 (FN1), which is related to migration; FLT4 involved in angiogenesis; GSK3B, an anti-proliferative enzyme; KPNA2, a nucleopore transporter and the EP300-associated transcriptional activator NCOA3." (PMID 28775339, 2017). "In models of breast cancer, the release of norepinephrine induced by stress stimulates cancer cells to secrete VEGFC, which in turn fosters lymphangiogenesis, remodeling, and an increase in stromal expression of VEGFR3 (FLT4)." (PMID 41601691, 2026). "In situ and transgenic models of breast cancer, stress promotes the release of norepinephrine in the nervous system and activates the release of cancer-derived VEGFC to promote lymphangiogenesis and remodeling, and it also increased the expression of VEGFR3(FLT4) in stoma cells." (PMID 35338118, 2022).
Milroy disease (38 papers, 2006 to 2025). Milroy disease is a frequent form of primary lymphedema (see this term) characterized generally by painless, chronic lower-limb lymphedema found at birth or developing in the early neonatal period. "FLT4 variants cause Milroy disease, one of the main forms of hereditary primary lymphedema, and they also predispose to the tetralogy of Fallot, indicating the role of VEGFR3 in the primary development of the heart." (PMID 36496429, 2022). "Nevertheless, all the FLT4 mutations (missense or small in-frame deletions) known to cause Milroy disease have been located in 2 intracellular kinase domains (exons 17–26) and are assumed to interfere with the tyrosine kinase activation of the VEGFR3 receptor." (PMID 36496429, 2022). "Hereditary lymphedema type I is the result of a defect in the FLT4 gene, encoding vascular endothelial growth factor receptor-3." (PMID 17194183, 2006). "For example, patients with Milroy’s disease, one of the most extensively studied hereditary congenital lymphedema disorders, have inactivating autosomal dominant mutations within the Fms-related tyrosine kinase 4 (FLT4) gene encoding VEGFR3 expression." (PMID 38201272, 2023). "Thus, evidence suggests that FLT4 mutations in Milroy disease have a dominant negative effect as they antagonize the activity of wild type protein." (PMID 33067626, 2021). "Recently, we and others have shown that FLT4 variants, distinct to those observed in Milroy disease cases, predispose individuals to Tetralogy of Fallot, the most common cyanotic congenital heart disease, demonstrating a novel function for VEGFR3 in early cardiac development." (PMID 33067626, 2021). "This study explored mutations in the Fms-related tyrosine kinase 4/vascular endothelial growth factor receptor 3 gene (FLT4) and lymphatic defects in patients with Milroy disease (MD)." (PMID 34681005, 2021). "Milroy disease (ORPHA79452; OMIM 153100) is the most common form, occurring as a result of pathogenic variants in FLT4/VEGFR3." (PMID 32409509, 2020). "Milroy disease is an autosomal dominant condition and approximately 70% of cases are caused by mutations in VEGFR3 (FLT4) with variable penetrance." (PMID 30071673, 2018). "Zebrafish are also used to model other primary lymphoedema subtypes including Milroy disease (fms-related receptor tyrosine kinase 4 (flt4, zebrafish orthologue of VEGFR3) mutant), Milroy-like disease (vegfc mutant), and Emberger syndrome (GATA-binding protein 2a (gata2a) mutant)." (PMID 40732363, 2025). "The identification of FLT4 as the causal or predisposing genetic factor for two unrelated human conditions, Milroy disease and TOF, respectively, highlights the distinct roles VEGFR3 plays in development." (PMID 33067626, 2021). "Milroy’s disease, the classic form of congenital lymphedema, is transmitted in an autosomal dominant manner and is determined by LOF of the VEGFR3 (vascular endothelial growth factor receptor 3 also called FLT4) gene, located on chromosome 5q35.3." (PMID 36293054, 2022). "In our patient group, we found no patients with Milroy disease, although that is the most common gene defect (FLT4) known in primary lymphedema at this time." (PMID 32998425, 2020).
lymph node metastasis (36 papers, 2003 to 2025). "Specifically, we demonstrated that elevated FLT4 was associated with lymph-node metastasis, advanced stage, and with early death from CRC." (PMID 25605009, 2015). "In our study, we showed that VEGF-C, VEGF-D, and Flt-4 were significantly correlated with lymph node metastasis and lymphatic vessel invasion." (PMID 19589137, 2009). "Similarly, Flt-4 expression was only associated with lymph node metastasis and lymphatic vessel invasion, but not with the other factors analyzed." (PMID 19589137, 2009). "In the current study, we found that in cervical carcinoma, Flt-4 was expressed not only in blood vessel and lymphatic vessel endothelial cells, but also in tumor cells, and that the level of Flt-4 was positively correlated with lymph node metastasis and lymphatic vessel infiltration." (PMID 19589137, 2009). "Furthermore, increased FLT4 was found to correlate with advanced clinical stage and with the presence of lymph node metastasis, but not with gender and age." (PMID 25605009, 2015).
melanoma (34 papers, 2003 to 2025). A malignant, usually aggressive tumor composed of atypical, neoplastic melanocytes. "Next, we performed double immunofluorescent staining for VEGF-C and Flt-4 in primary melanoma of the tongue, tumor-bearing SLNs, and LNs adjacent to tumor-bearing SLNs." (PMID 23031500, 2012). "In both tongue melanomas and tumor-bearing SLNs, close interaction was observed between VEGF-C-positive melanoma cells and Flt-4-positive lymphatic vessels." (PMID 23031500, 2012). "Recently, however, overexpression of VEGF-C had been shown to stimulate lymphangiogenesis in xenotransplanted human melanomas, and in the chick chorioallantoic membrane, and this occurs through activation of VEGF receptor 3 (flt-4) in lymphatic endothelial cells." (PMID 14760386, 2004). "In this context, the FLT4 antagonist, MAZ51, significantly reduced peri- and intratumoral melanoma cells’ proliferation by decreasing the number of lymphatic vessels and capillaries into mice lungs with induced melanoma." (PMID 34638342, 2021).